BTG2 (BTG anti-proliferation factor 2)
Description:
Anti-proliferative protein; the function is mediated by association with deadenylase subunits of the CCR4-NOT complex. Activates mRNA deadenylation in a CNOT6 and CNOT7-dependent manner. In vitro can inhibit deadenylase activity of CNOT7 and CNOT8. Involved in cell cycle regulation. Could be involved in the growth arrest and differentiation of the neuronal precursors (By similarity). Modulates transcription regulation mediated by ESR1. Involved in mitochondrial depolarization and neurite outgrowth.
Synonyms: PC3; TIS21; MGC126063; MGC126064; APRO1
Tractability: PROTAC: ubiquitination databases record sites on it.
Gene: Protein-coding gene on chromosome 1 (203,305,491 to 203,309,602, forward strand). Ensembl gene ENSG00000159388.
Subcellular location (Human Protein Atlas): Vesicles; Nucleoplasm
Gene Ontology:
Molecular function: protein binding; transcription corepressor activity
Biological process: DNA damage response; negative regulation of cell population proliferation; negative regulation of translation; neuron projection development; positive regulation of nuclear-transcribed mRNA poly(A) tail shortening; DNA repair; cellular response to phorbol 13-acetate 12-myristate; negative regulation of DNA-templated transcription; negative regulation of neuron apoptotic process; response to electrical stimulus; response to mechanical stimulus; response to peptide hormone
Cellular component: extracellular exosome; cytoplasm; cytosol; nucleus
Genetic constraint (gnomAD): Loss-of-function variants: 9 observed, 13.17 expected, observed/expected ratio (o/e) 0.68, 90% interval 0.41 to 1.19. The upper end of that interval is the gene's LOEUF score, 1.19, which puts it in group 5 of 6, group 1 being the genes least tolerant of losing a copy. Missense variants: 200 observed, 205.03 expected, observed/expected ratio (o/e) 0.98, 90% interval 0.87 to 1.1. Synonymous variants: 92 observed, 86.69 expected, observed/expected ratio (o/e) 1.06, 90% interval 0.9 to 1.26.
Homologues: Orthologues: chimpanzee BTG2 (100% identical), macaque BTG2 (99% identical), guinea pig BTG2 (95% identical), pig BTG2 (95% identical), mouse Btg2 (94% identical), rabbit BTG2 (93% identical), rat Btg2 (92% identical), dog BTG2 (89% identical), zebrafish btg2 (60% identical), tropical clawed frog btg2 (58% identical). Paralogues in human: BTG1 (66% identical), BTG3 (32% identical), BTG4 (30% identical).
Diseases named in the same sentence as BTG2 in open-access papers:
BTG2 is named in the same sentence as 124 diseases in open-access papers, as found by Europe PMC text mining. Sharing a sentence is not in itself a finding about the gene and the disease. The quoted sentences say what the papers report.
breast carcinoma (48 papers, 2007 to 2025). "Remarkably, the infusion of BTG2-deficient mast cells reduced chemotherapy efficacy and increased lymph node metastasis in the breast cancer mouse model, compared to untreated mast cells." (PMID 40313959, 2025). "It has been discovered that the downregulation of BTG2 is linked with substandard breast carcinoma prognosis." (PMID 36157236, 2022). "Studies have shown that the expression level of BTG2 is low in breast cancer cell lines and is associated with tumor grade, size, metastasis, recurrence and breast cancer survival." (PMID 36591524, 2022). "The lower the level of BTG2 expression, the higher the risk of lymphatic invasion and vascular invasion in breast cancer patients, and the higher the risk of tumor metastasis." (PMID 36591524, 2022). "BTG2 expression is downregulated in many human cancers, which is associated with poor prognosis in breast cancer patients." (PMID 29310680, 2018). "This is the first report of a large quantitative analysis demonstrating that BTG2 expression is associated with breast cancer patient survival." (PMID 20553615, 2010). "Likewise, protein expression levels of BTG2 have also been found to be associated with 5-year overall survival in breast cancer patients." (PMID 30961553, 2019). "The Tis21 gene (also known as PC3 or Btg2, in rat and human) encodes a transcriptional cofactor that functions as a tumor suppressor protein in prostate cancer cells, in renal cancer development and in breast cancer." (PMID 29538458, 2018). "Furthermore, the loss of BTG2 expression is related significantly with tumor grade, metastasis and resistance to cancer treatment, especially in the estrogen receptor positive breast cancers." (PMID 24047462, 2013). "Our study fills the gap in the research field of the BTG2 gene in mast cells and provides a new specific target molecule for the development of chemotherapy resistance strategies for breast cancer." (PMID 40313959, 2025). "DCFH-DA, as a marker for ROS detection, was more stained in mast cells isolated in situ from chemotherapy-resistant breast cancer patients, and showed a higher degree of staining in mast cells of the BTG2 low expression group in in vitro cell experiments." (PMID 40313959, 2025). "Collectively, these findings indicate that LDRT enhances chemotherapy sensitivity in breast cancer by upregulating BTG2 expression in mast cells, thereby reprogramming the TME toward a more immunostimulatory state." (PMID 40313959, 2025). "Here, we found that mast cells, characterized by low expression of BTG2, were enriched in the in situ tumor tissue and draining lymph nodes of patients with neoadjuvant chemotherapy-resistant breast cancer." (PMID 40313959, 2025). "BTG2 has been proven to be downregulated in breast cancer, liver cancer, lung cancer, colorectal cancer and other tumors, and is closely related to the malignancy, recurrence and metastasis of the tumor." (PMID 40313959, 2025). "This study highlights the immunoregulatory role of mast cells in the breast cancer tumor microenvironment and establishes a link between BTG2 expression in mast cells and neoadjuvant chemotherapy response." (PMID 40313959, 2025). "In this study, we identified a mast cell subpopulation associated with resistance to neoadjuvant chemotherapy, characterized by low BTG2 expression, through scRNA sequencing of primary breast cancer samples and paired metastatic lymph nodes." (PMID 40313959, 2025). "BTG2 can inhibit tumor growth and progression in breast cancer by suppressing the tumor microenvironments by regulating the mTORc2-AKT1-NFAT1-PHLPP2 signaling cascade." (PMID 36765032, 2023). "BTG2 expression level has been found to be correlated with the clinical characteristics of the tumor in breast cancer samples." (PMID 36591524, 2022).
breast carcinoma (continued). "In breast carcinoma, low BTG2 expression is related to increased tumor grade, disease progression and poor overall survival." (PMID 34217312, 2021). "For example, miR-92a-3p regulated breast cancer cell proliferation and metastasis via regulating B-cell translocation gene 2 (BTG2)." (PMID 35095494, 2021). "BTG2 is a newly identified tumor suppressor that belongs to the BTG/TOB family, and many studies have revealed that BTG2 is downregulated in various cancers, including breast cancer, osteosarcoma, and bladder cancer." (PMID 31959200, 2020). "BTG2 expression is decreased in various tumor tissues such as breast cancer, lung cancer, bladder cancer and HCC, and the low expression of BTG2 is associated with the aggressive clinical manifestations and poor prognosis." (PMID 30621734, 2019). "We hereby presented the new role of BTG2/TIS21 gene as an inhibitor of Twist1 translation in the TNBC cells and the phenomenon was evidenced in tissues of the BTG2/TIS21-KO mice and human breast cancers." (PMID 31138781, 2019). "Previous studies showed G2/M cell-cycle arrest induced by upregulation of CCNG2 and BTG2 in human breast cancer cells." (PMID 31758045, 2019). "It has also been shown that decrease of BTG2 expression in human breast cancer correlates with disease progression." (PMID 30961553, 2019). "Reduced expression of BTG2 is found to be related to tumor size, grade, metastasis, recurrence and poor survival in patients with breast cancer." (PMID 29310680, 2018). "Further, BTG2 expression has also been found to be related to prognosis in bladder cancer, breast cancer and pancreatic cancer." (PMID 29656435, 2018). "In breast cancer cells, it was demonstrated that the estrogen receptor alpha plays a role in the reduction of BTG2 promoter activity." (PMID 30115961, 2018). "In a breast cancer study, it was demonstrated that estradiol suppressed the BTG2 promoter in MCF-7 and Hela cells." (PMID 30115961, 2018). "It was also found that there was a negative correlation between the expression levels of miR-25 and BTG2 in breast cancer specimens at the mRNA level from TCGA database (Pearson’s correlation, r = −0.243, P < 0.05)." (PMID 29310680, 2018). "Low BTG2 expression correlated with decreased overall survival and metastasis-free survival of breast cancer patients, indicating that BTG2 is a clinically relevant suppressor of breast tumor progression." (PMID 26818199, 2016). "Down-regulation of BTG2 has been observed in several cancer types such as prostate cancer, breast cancer and gliomas." (PMID 20553615, 2010). "We conclude that high-level BTG2 protein expression correlates with prolonged survival in patients with breast carcinoma." (PMID 20553615, 2010). "In this study 78% of the breast cancer samples showed moderate to high expression of BTG2 in the majority of tumour cells." (PMID 20553615, 2010). "The overexpressed BTG2 could reduce the proliferation and migration of various types of cancer cells, which may also act as an effective target for the treatment of breast cancer." (PMID 40918450, 2025). "For instance, BTG2 decrease promoted breast cancer's metastasis." (PMID 36816363, 2023). "Many investigations have indicated that BTG2 overexpression could stimulate cellular apoptosis and restrain cell invasion in prostate cancer, medulloblastoma, and breast cancer." (PMID 36157236, 2022). "Studies have found that the expression of BTG2 is decreased in various tumor tissues such as prostate cancer, renal cell carcinoma and HCC, and it has been confirmed to be associated with poor prognosis of breast cancer, bladder cancer and lung cancer." (PMID 30621734, 2019). "We further performed a dual-luciferase reporter assay to identify whether BTG2 was a direct target of miR-25-3p in breast cancer." (PMID 29310680, 2018). "Decreased BTG2 was related with poor relapse free survival (RFS) in all subtypes of breast cancer." (PMID 28922388, 2017).
breast carcinoma (continued). "In addition, reduced BTG2 expression correlated with reduced overall survival as well as metastasis-free survival of breast cancer patients, consistent with previous reports." (PMID 26818199, 2016). "BTG2 is therefore a promising prognostic marker in breast cancer." (PMID 20553615, 2010). "We conclude that high BTG2 expression levels correlate with prolonged breast cancer survival." (PMID 20553615, 2010). "Thus, we could hypothesize that BTG2/TIS21-inhibited cancer invasion might be through the downregulation of Twist1 activity in human breast cancers." (PMID 31138781, 2019). "Both BTG1 and BTG2 may act as the negative regulator to breast cancer cells." (PMID 29416786, 2018). "Furthermore, we put forward BTG2 could act as a prognostic biomarker for breast cancer, especially for the subtype of luminal A, as well as this family may be prognostic biomarkers for lung adenocarcinoma." (PMID 28922388, 2017). "Thus, in addition to its predictive value in other subtypes of breast cancer, BTG2 expression may be a prognostic marker for TNBC." (PMID 26818199, 2016). "To investigate whether epigenetic silencing is involved in suppressing BTG2 expression in proliferating cells, we measured BTG2 induction in the human breast cancer cell line MDA-MB-231, following infection with an arrayed lentiviral shRNA library containing shRNAs against 43 KMTs." (PMID 26394836, 2015). "Furthermore, BTG2 protein expression may be used as a prognosticator for breast cancer as well as a possible molecular target in breast cancer treatment." (PMID 20553615, 2010). "A previous study demonstrated that miR-25-3p functions as an oncogene and promotes proliferation via the induction of B-cell translocation gene 2 (BTG2), another member of the APRO protein family, in breast cancer." (PMID 40918450, 2025). "A previous research revealed that elevated BTG2 could enhance the responsiveness to Tamoxifen in estrogen receptor-positive breast cancer (BC) patients." (PMID 38062199, 2023). "We identified 4 mRNAs (TPD52, BTG2, CCND2, LIFR) involved in the prognosis of breast cancer using survival analysis." (PMID 34545330, 2021). "The overall survival data showed that the prognosis of breast cancer patients was poorer when two genes (FOS and FOSB) were highly expressed or when four genes (JUN, GADD45B, NR4A1, and BTG2) showed low expression levels." (PMID 34457116, 2021). "BTG2 expression negatively correlated with miR-25-3p expression, where BTG2 expression was downregulated while miR-25-3p was upregulated in TNBC samples compared to normal and luminal breast cancer samples." (PMID 29310680, 2018). "In TCGA database, BTG2 expression was available for 115 TNBC and 821 luminal breast cancer samples and it was lower in TNBC samples compared with lumial breast cancer samples." (PMID 29310680, 2018). "Previous studies have shown that the ADIPOR1, ADORA1, BTG2 and CD46 genes differ significantly between long-term survivors of breast cancer and deceased patients, both in levels of gene expression and DNA copy numbers." (PMID 20553615, 2010). "Thirdly, there is a lack of long-term survival and prognosis analysis for breast cancer patients with low BTG2 expression in mast cells, limiting the broader applicability of our findings." (PMID 40313959, 2025). "The results showed that five lncRNAs including HOTAIR, DANCR, PVT1, LINC00511, and NEAT1 and 16 miRNAs and five of their targets—VEGFA, BTG2, E2F3, IRAK1, and SMAD4—have significantly different expression patterns in normal individuals compared to those with breast cancer." (PMID 36726376, 2023). "In addition, relapse-free survival rates of breast cancers (both HER2+ and HER2−) were negatively correlated with the level of Twist1, but positively correlated with BTG2 expression by open data analysis." (PMID 31138781, 2019). "Initially, we screened various breast cancer cells with and without invasiveness to identify if BTG2 and Twist1 expressions are mutually exclusive." (PMID 31138781, 2019).
breast carcinoma (continued). "Furthermore, BTG2 can also inhibit proliferation, invasion, and induce apoptosis in MDA-MB-231 breast cancer cells." (PMID 29310680, 2018). "Furthermore, BTG2 mediated-IκBα degradation was confirmed also in MCF7 breast cancer cells and wt-MEF after transfections of BTG2 cDNAs and siBTG2/TIS21, respectively." (PMID 24047462, 2013). "A previous study analysed BTG2 protein expression and correlated decreased nucleus expression to a more aggressive phenotype of breast cancer, although they did not detect a significant difference in survival." (PMID 20553615, 2010). "Based on their involvement in breast cancer and the availability of commercial antibodies, the ADIPOR1, ADORA1, BTG2 and CD46 genes were selected among the 27 previously identified genes to further investigate the association of protein expression levels to overall patient survival." (PMID 20553615, 2010).
prostate carcinoma (24 papers, 2005 to 2025). A carcinoma that arises from epithelial cells of the prostate gland. "B-cell translocation gene 2 (BTG2) is a basal protein that has been implicated in prostate cancer transformation and progression and also possesses anti-proliferative activity." (PMID 27588490, 2016). "It's up-regulation in prostate cancer is associated with increased severity, possibly due to the downregulation in BTG2." (PMID 24029073, 2013). "Prostate cancer studies demonstrate miR-32-5p targeting of BTG2 (BTG Anti-Proliferation Factor 2), which regulates cell cycle progression and DNA damage responses." (PMID 40711670, 2025). "For example, the introduction of BTG2, a tumor suppressor gene lost in metastatic lung and prostate cancers, repressed cell migration and cancer invasion by the inhibition of mitochondrial ROS as well as Src activity." (PMID 35565279, 2022). "Previous reports suggest that BTG2 is downregulated in various malignant tumors, including prostate cancer, lung cancer, and hepatic cell carcinoma." (PMID 36157236, 2022). "In prostate cancer, BTG2 suppression promotes disease progression, therapy resistance, and metastasis." (PMID 34217312, 2021). "The results are in agreed with our previous studies which verified that ectopic overexpression of NIK via the NF-κB pathways upregulated migration and invasion enhancer 1 (MENI) but downregulated BTG2 in the prostate carcinoma cells." (PMID 33802402, 2021). "In prostate cancer, BTG2 is a target of miR‐32, miR‐21, and its suppression results in disease initiation and progression, therapy resistance, and metastasis." (PMID 30350856, 2019). "BTG2 is frequently downregulated in prostate cancer, and its reduced expression is correlated with development of castration-resistant prostate cancer, suggesting that BTG2 plays an important role in suppression of prostate cancer progression." (PMID 30863497, 2019). "By analyzing the GEO database, we found that the level of BTG2 was significantly upregulated in several cancers, including lung cancer and prostate cancer, after PRMT5 knockdown." (PMID 29441724, 2018). "In Yu’s study, we found that BTG2 was increased in prostate cancer (fold change = 2.258, t = 7.407, p = 7.27E-11)." (PMID 28922388, 2017). "Overexpression of miR-21 in prostate cells promotes EMT leading to the transformation of normal prostate cells into prostate cancer cells primarily from repression of B-cell translocation gene 2 (BTG2)." (PMID 27588490, 2016). "Cisplatin enhanced BTG2 gene expression dependent on the DNA fragment located within -173 to -82 upstream of BTG2 translation initiation site in prostate cancer cells." (PMID 24981574, 2014). "Our objectives for this study are to determine the effects of cisplatin on prostate cancer cell growth, the AR and PSA expression, as well as the regulatory mechanisms of cisplatin on the gene expression of BTG2 in prostate cancer cells." (PMID 24981574, 2014).